TRAV12-3 (T cell receptor alpha variable 12-3)
Description:
V region of the variable domain of T cell receptor (TR) alpha chain that participates in the antigen recognition. Alpha-beta T cell receptors are antigen specific receptors which are essential to the immune response and are present on the cell surface of T lymphocytes. Recognize peptide-major histocompatibility (MH) (pMH) complexes that are displayed by antigen presenting cells (APC), a prerequisite for efficient T cell adaptive immunity against pathogens. Binding of alpha-beta TR to pMH complex initiates TR-CD3 clustering on the cell surface and intracellular activation of LCK that phosphorylates the ITAM motifs of CD3G, CD3D, CD3E and CD247 enabling the recruitment of ZAP70. In turn ZAP70 phosphorylates LAT, which recruits numerous signaling molecules to form the LAT signalosome. The LAT signalosome propagates signal branching to three major signaling pathways, the calcium, the mitogen-activated protein kinase (MAPK) kinase and the nuclear factor NF-kappa-B (NF-kB) pathways, leading to the mobilization of transcription factors that are critical for gene expression and essential for T cell growth and differentiation. The T cell repertoire is generated in the thymus, by V-(D)-J rearrangement. This repertoire is then shaped by intrathymic selection events to generate a peripheral T cell pool of self-MH restricted, non-autoaggressive T cells. Post-thymic interaction of alpha-beta TR with the pMH complexes shapes TR structural and functional avidity.
Synonyms: TRAV123; TCRAV2S2; TCRAV12S3
Gene: T-cell receptor variable (V) gene on chromosome 14 (21,965,451 to 21,966,061, forward strand). Ensembl gene ENSG00000211794.
Subcellular location: Cell membrane
Gene Ontology:
Molecular function: peptide antigen binding
Cellular component: plasma membrane
Homologues: Orthologues: macaque TRAV12-3 (74% identical), mouse Trav7-3 (65% identical), mouse Trav7d-3 (65% identical), mouse Trav7d-4 (63% identical), mouse Trav7n-4 (63% identical), mouse Trav7-4 (62% identical), mouse Trav7-1 (61% identical), rat Trav12-3 (61% identical), mouse Trav7-2 (60% identical), mouse Trav7d-2 (60% identical), mouse Trav7d-6 (59% identical), mouse Trav7n-6 (59% identical), and 4 more. Paralogues in human: TRAV12-2 (78% identical), TRAV12-1 (75% identical), TRAV23DV6 (48% identical), TRAV29DV5 (48% identical).
Diseases named in the same sentence as TRAV12-3 in open-access papers:
TRAV12-3 is named in the same sentence as 1 disease in open-access papers, as found by Europe PMC text mining. Sharing a sentence is not in itself a finding about the gene and the disease.
TRAV12-3 shares sentences with these, for which no sentence is quoted: autoimmune disease (1 paper).